NECAB2 (N-terminal EF-hand calcium binding protein 2)
Description:
May act as a signaling scaffold protein that senses intracellular calcium. Can modulate ligand-induced internalization of ADORA2A and coupling efficiency of mGluR5/GRM5; for both receptors may regulate signaling activity such as promoting MAPK1/3 (ERK1/2) activation.
Synonyms: Stip-2; EFCBP2
Tractability: Antibody: UniProt places it where antibodies can reach, with high confidence; its Gene Ontology location is reachable by antibodies, with high confidence. PROTAC: its protein half-life has been measured.
Gene: Protein-coding gene on chromosome 16 (83,968,244 to 84,002,776, forward strand). Ensembl gene ENSG00000103154.
Subcellular location: Cytoplasm; Cell projection, dendrite; Cell projection, axon; Cell membrane
Gene Ontology:
Molecular function: A2A adenosine receptor binding; protein binding; type 5 metabotropic glutamate receptor binding; calcium ion binding
Biological process: negative regulation of G protein-coupled receptor internalization; positive regulation of adenosine receptor signaling pathway; positive regulation of ERK1 and ERK2 cascade; positive regulation of glutamate receptor signaling pathway; positive regulation of protein localization to membrane; regulation of amyloid precursor protein biosynthetic process
Cellular component: plasma membrane; cytoplasm; axon; dendrite; postsynapse; presynapse
Genetic constraint (gnomAD): Loss-of-function variants: 68 observed, 48.53 expected, observed/expected ratio (o/e) 1.4, 90% interval 1.15 to 1.71. The synonymous counts are far from expectation, so gnomAD's model fits this gene poorly and the ratio says little. Missense variants: 853 observed, 486.27 expected, observed/expected ratio (o/e) 1.75, 90% interval 1.66 to 1.86. Synonymous variants: 329 observed, 197.96 expected, observed/expected ratio (o/e) 1.66, 90% interval 1.52 to 1.82.
Homologues: Orthologues: chimpanzee NECAB2 (98% identical), macaque NECAB2 (94% identical), dog NECAB2 (87% identical), mouse Necab2 (86% identical), rat Necab2 (85% identical), guinea pig NECAB2 (72% identical), zebrafish necab2 (61% identical), tropical clawed frog necab2 (60% identical). Paralogues in human: NECAB1 (38% identical), NECAB3 (35% identical).
Diseases named in the same sentence as NECAB2 in open-access papers:
NECAB2 is named in the same sentence as 10 diseases in open-access papers, as found by Europe PMC text mining. Sharing a sentence is not in itself a finding about the gene and the disease. The quoted sentences say what the papers report.
Anxiety (2 papers, 2022 to 2023). Intense feelings of nervousness, tension, or panic often arise in response to interpersonal stresses. "This protein network insinuates a mechanism whereby Necab2—Adora2a interaction reduces Adora2a plasma membrane expression, creating an environment where more dopamine can bind to its receptor and potentially protect against anxiety-like behaviors." (PMID 37228107, 2023).
autism spectrum disorder (2 papers, 2021 to 2022). A spectrum of developmental disorders that includes autism, and Asperger syndrome. "De novo deletion of the neuronal calcium-binding protein 2 (NECAB2) locus is associated with idiopathic autism spectrum disorders (ASDs)." (PMID 35909444, 2022).
autism (1 paper, 2022). Persistent deficits in social interaction and communication and interaction as well as a markedly restricted repertoire of activity and interest as well as repetitive patterns of behavior. "A proteomic study involving yeast two-hybrid screening showed that NECAB2 interacts with five autism-risk genes (FMR1, FXR1, FXR2, SMARCA2, and TSC1)." (PMID 35909444, 2022).
colorectal cancer (1 paper, 2025). A primary or metastatic malignant neoplasm that affects the colon or rectum. "NECAB2, primarily involved in regulating neuronal calcium homeostasis, and KCNJ16, which controls potassium ion flow, have not been previously linked to colorectal cancer development." (PMID 40432804, 2025).
cancer (3 papers, 2016 to 2022). A tumor composed of atypical neoplastic, often pleomorphic cells that invade other tissues. "In order to verify reliable GRSDMs, 22 specific DNA methylation genes related to prognosis obtained in the training set were verified on 11 sets of GEO data, and 8 of the specific DNA methylation genes (DGRK, F2RL3, GRK5, NECAB2, OR1C1, OR2L13, OR6F1, and PIK3R6) had been verified in pan-cancer." (PMID 35885996, 2022). "Using RT-PCR, we found NECAB2 and NECAB3, but not NECAB1, to be expressed in cancer cells." (PMID 26948053, 2016).
infection (1 paper, 2024). The state of being infected such as from the introduction of a foreign agent such as serum, vaccine, antigenic substance or organism. "The Necab2 gene was shown to be downregulated in zebrafish larvae upon Vibrio parahaemolyticus infection and upregulated upon infection in Notch-knockout larvae." (PMID 39768135, 2024).
tumours (1 paper, 2024). "N-terminal EF-hand calcium-binding protein 2 (NECAB2) is mainly involved in the regulation of calcium homeostasis in neurons, and only a few studies focused on NECAB2 expression in tumours." (PMID 38168553, 2024).
NECAB2 also shares sentences with these, for which no sentence is quoted: astrocytoma (1 paper); Cognitive impairment (1); gastric cancer (1).